CCL19 (C-C motif chemokine ligand 19)
Diseases named in the same sentence as CCL19 in open-access papers (continued):
Sharing a sentence is not in itself a finding about the gene and the disease.
infection (continued). "However, CCL19-treated resting CD4+ T cells had a pattern of integration that differed significantly from the other in vitro conditions, suggesting HIV integration site selection may depend on the balance of transcription factors, including NF-κB, at the time of infection." (PMID 27459960, 2016). "Conversely, there was no significant increase in mRNA expression of CCL5, CCL19, CCL20 and CCL21 chemokines after infection in both MyD88+/+ and MyD88−/− mice." (PMID 23374751, 2013). "On day 7 p.i., in addition to chemokines upregulated on day 3 p.i., lethal infection further induced higher expression of CCL2, CCL6, CCL11, CCL19, CCR7, CXCR1, and CXCL11 compared to nonlethal infection." (PMID 23526993, 2013). "Latency can be established in vitro by direct infection of resting CD4+ T-cells in the presence of stimuli, including the chemokine CCL19; high viral titres with or without spinoculation; or culturing T-cells in contact with myeloid dendritic cells [mDC,] or endothelial cells." (PMID 27383184, 2016).
infectious disease (4 papers, 2009 to 2022). A disorder directly resulting from the presence and activity of a microbial, viral, or parasitic agent in humans. "Elevated levels of CCL19 in the CSF of patients with various infectious diseases (including LNB patients) were determined by two study groups with a mean value between 173 - 250 pg/ml compared to 26 - 62 pg/ml in NIND patients." (PMID 20042073, 2009). "Despite the fact that CCL19 and CCL21 are mainly produced in secondary lymphoid tissue, CCL19 and CCL21 production in non-lymphoid organs has been observed during inflammatory and infectious diseases." (PMID 29085362, 2017).
adenocarcinoma (3 papers, 2011 to 2020). A common cancer characterized by the presence of malignant glandular cells. "The positive correlation between ACKR4 expression in neoplastic tissue and CCL19 was weak but present in both polyps and adenocarcinomas." (PMID 33374792, 2020).
immune dysfunction (3 papers, 2017 to 2024). "Hence, ASD-induced decreases in peripheral blood CCL19 and TNFSF11 levels may further exacerbate immune system disorders." (PMID 38742104, 2024).
colon polyps (2 papers, 2022 to 2025). "In summary, our MR analysis has provided genetic evidence supporting the causal effects of multiple inflammatory factors – such as CCL19, CD40L, CCL20, PD-L1, IL-5, and M-CSF – on 5 distinct intestinal diseases (IBD, UC, CD, CAC, and CRC)." (PMID 41239614, 2025). "The colon polyps demonstrated decreased expressions in CCL5, CCL18, CCL19, CCL21, CXCL12, CXCL14 and CXCL13 genes in this research." (PMID 35486660, 2022).
hematological malignancies (1 paper, 2024). "More generally, CCR7 signalling upon binding to its ligands (CCL19/21) is associated with many pro-tumorigenic effects in hematological malignancies, including migration, proliferation, survival and immune evasion." (PMID 40809150, 2024).
inflammation (1 paper, 2014). Aberrant reaction of the microcirculation characterized by movement of fluid and leukocytes from the blood into extravascular tissues. "Thus, CCL19 might be involved in the pathogenesis of CNS inflammation and in the migration of inflammatory cells into the subarachnoid space." (PMID 25016392, 2014).
kidney diseases (1 paper, 2022). "The significant function of CCL19 in the pathogenesis of human kidney diseases has also been a concern." (PMID 35222545, 2022). "All the evidence demonstrates that CCL19 might be a critical biomarker and therapeutic target in human kidney diseases." (PMID 35222545, 2022).
neurologic disease (1 paper, 2014). "CCL19 was detectable in healthy dogs and in patients with idiopathic epilepsy, a non-inflammatory neurologic disease, which is in agreement with the results of other studies in that CCL19 is constitutively expressed in the CNS and linked to the physiological immunosurveillance." (PMID 25016392, 2014).
psychiatric disorder (1 paper, 2024). A disorder characterized by behavioral and/or psychological abnormalities, often accompanied by physical symptoms. "Elevated levels of chemokines such as CCL19 have been found in neuroinflammatory diseases and psychiatric disorders such as SZ, suggesting a potential link to it." (PMID 39544374, 2024).
CCL19 also shares sentences with these, for which no sentence is quoted: bacterial infection (3 papers); aortic aneurysm (2); colorectal adenocarcinoma (2); endothelial dysfunction (2); inflammatory bowel disease (2); interstitial lung disease (2); lichen planus (2); myocardial infarction (2); osteoporosis (2); small cell lung carcinoma (2); Splenomegaly (2); acute respiratory distress syndrome (1); airways allergies (1); allergic conjunctivitis (1); Allergy (1); Alzheimer disease (1); anaphylaxis (1); aneurysm (1); aortic valve disease (1); astrocytoma (1); brain ischemia (1); brain tumors (1); Carcinoid (1); carcinoma in situ (1); cardiac hypertrophy (1); cardiovascular disease (1); central nervous system disorder (1); cerebrovascular disease (1); cholangiocarcinoma (1); chronic thromboembolic pulmonary hypertension (1).
A further 68 diseases each share a sentence with CCL19 in 1 paper.